TNF (tumor necrosis factor)
Diseases named in the same sentence as TNF in open-access papers (continued):
Sharing a sentence is not in itself a finding about the gene and the disease.
neurosarcoidosis (19 papers, 2011 to 2026). A sarcoidosis that involves the nervous system. "In conclusion, this case of paradoxical neurosarcoidosis induced by TNFα blockade in a RA patient underlines the risk to destabilize autoimmune profile when using targeted therapies and promote unexpected immune disease." (PMID 24373564, 2013). "Recent research has highlighted the potential of tumor necrosis factor‐alpha (TNF‐α) inhibitors in managing refractory neurosarcoidosis." (PMID 38087813, 2024). "Adalimumab, another TNF-α inhibitor, has also shown efficacy in case series of neurosarcoidosis patients." (PMID 39398844, 2024). "Tumor necrosis factor-alpha (TNF-α) inhibitors have shown promising results in the treatment of refractory neurosarcoidosis." (PMID 39398844, 2024). "In a recent literature review, the proportion of a favorable outcome in patients with neurosarcoidosis treated with TNF-alpha inhibitor was higher, compared to methotrexate, MMF and AZA (p < 0.00001)." (PMID 37568942, 2023). "The second objective of our study was to perform a comparative literature review of neurosarcoidosis, with a focus on treatment outcomes with the use of TNF-α antagonist." (PMID 36388212, 2022). "Comparison of treatment outcomes of neurosarcoidosis according to treatment between azathioprine, methotrexate, and mycofenolate mofetil, respectively, and TNF-alpha antagonist." (PMID 36388212, 2022). "The results of our cohort and literature review provide relevant results regarding treatment with TNF-α antagonists and confirm their effectiveness in neurosarcoidosis." (PMID 36388212, 2022). "Eighty percent presented favorable outcomes following anti-TNF-α therapy, while mortality related to neurosarcoidosis was reported in only one patient." (PMID 36388212, 2022). "Combined disease characteristics, management, and outcomes of neurosarcoidosis cases treated with the anti-TNF-α antagonist from our cohort (n = 2) and the literature (n = 404)." (PMID 36388212, 2022). "Including our study, we identified 25 studies reporting 406 patients diagnosed with neurosarcoidosis and treated with TNF-α antagonists." (PMID 36388212, 2022). "Recent studies provided class IV evidence that TNF-α antagonists are also beneficial in neurosarcoidosis." (PMID 36388212, 2022). "Infliximab, among anti-TNF agents, is effective in refractory pulmonary, cutaneous, and neurosarcoidosis." (PMID 35772032, 2022). "Third-line treatments such as TNF-α antagonists are increasingly used in the management of neurosarcoidosis." (PMID 36388212, 2022). "We found that TNF inhibitor exposure occurred most often in patients with neurosarcoidosis, meningoencephalitis, and lepto-pachymeningitis (>50% exposed)." (PMID 32421186, 2020). "Anti–TNF-α agents are effective in the treatment of other CNS diseases, such as neurosarcoidosis, likely because of a leaky BBB." (PMID 30608049, 2019). "Over time, second and third line therapy emerged into the treatment of neurosarcoidosis, most recently TNF-alpha antagonists." (PMID 27846819, 2016). "We present the case of a 40-year-old woman, with a confirmed erosive and seropositive RA, successfully treated by TNFα blocker (etanercept) for seven years, and who developed a severe neurosarcoidosis." (PMID 24373564, 2013). "Azathioprine and methotrexate are “traditional” immunosuppressive agents commonly used, though their clinical effect can take months to appear, and anti-TNF (tumor necrosis factor) monoclonal antibodies are increasingly being introduced early in the immunosuppressive treatment of neurosarcoidosis." (PMID 39198811, 2024). "IL-6, BAFF, CXCL9, CXCL10, CXCL13, GM-CSF, IFN-gamma, and TNF-alpha levels were significantly elevated in CSF from neurosarcoidosis patients compared to controls (p<0.0001), along with IL-2 (p=0.0002), IL-8/CXCL8 (p=0.0008), IL-10 (p=0.0005), and IL-13 (p=0.0018)." (PMID 39398844, 2024). "Anti-TNFα agents are becoming one of the cornerstone treatments for neurosarcoidosis." (PMID 38255684, 2023).
neurosarcoidosis (continued). "Recent evidence indicates that other anti TNF agents, such as adalimumab, may also be effective in neurosarcoidosis." (PMID 38255684, 2023). "In up to 70% of patients, corticosteroids could be tapered or even stopped, confirming the role of anti-TNF-α as efficient corticosteroid-sparing agents even in cases of refractory or aggressive neurosarcoidosis." (PMID 36388212, 2022). "These three cases raise the issue of TNFα blockers imputability on the onset of neurosarcoidosis." (PMID 24373564, 2013). "TNFα blockers have already been associated in some cases with “paradoxical” systemic sarcoidosis but only two cases of neurosarcoidosis have been reported and none with etanercept." (PMID 24373564, 2013). "Clinicians should consider neurosarcoidosis and MOGAD in patients on TNF-α-inhibitors presenting with neurological deficits, even in the absence of radiological findings." (PMID 42305552, 2026). "A systematic review and meta‐analysis from 2016 that focused on the clinical features, treatments, and outcomes of neurosarcoidosis patients did not report the proportional rate of positive outcomes in patients receiving TNF‐alpha antagonist therapy." (PMID 38087813, 2024). "Although new treatments such as TNF-alpha antagonists are increasingly used, the mortality rate in patients with neurosarcoidosis remains at 5% and about one third of patients do not experience significant clinical improvement with treatment." (PMID 38255684, 2023). "Although new treatments, such as TNF-alpha antagonists, are increasingly used, the mortality rate among patients with neurosarcoidosis remains 5% and about one third does not have a substantial clinical improvement on treatment." (PMID 27846819, 2016).
otitis media (19 papers, 2009 to 2025). Inflammation of the anatomical structures of the middle ear, which is most often caused by an infectious process. "Previous candidate gene studies associated a number of immune system genes with otitis media, which included TNF-α, IL-6, IL-10, Tlr4, surfactant, CD14, FcγRIIa, IFNγ, Eya4, p73, MyD88, Fas, E2f4, Plg, Fbxo11, and Evi1." (PMID 24466073, 2014). "A TNF -308 polymorphism was associated with both otitis media susceptibility and placement of tympanostomy tubes." (PMID 19728873, 2009). "In vivo experiments utilizing a rat model of otitis media demonstrated a significant reduction in the levels of pro-inflammatory cytokines TNF-α, IL-1β, TLR4, and IL-6, and greater levels of Nrf-2 and SOD in comparison to untreated controls." (PMID 40143156, 2025). "In this study, using a model that causes otitis media (OM), a disease with a high incidence in children, we confirmed the efficacy of MSC-derived EV to reduce inflammatory factors (TNF-, COX-2, IL-1, and IL-6)." (PMID 34016123, 2021). "Inflammatory cytokines such as IL1α, IL1β, and tumor necrosis factor produced by macrophages and monocytes in response to microbial toxin play a vital role in middle ear inflammation and OM." (PMID 32391052, 2020). "Otitis media are accompanied by raised expression of vascular endothelial growth factor, TNF-α and IL-1β in ear fluids, during which TGIF1 mutants illustrate auditory deficits." (PMID 33414721, 2020). "Trans-tympanic membrane treatment of mice with sTNFRI and anti-TNF-alpha inhibits LPS induced middle ear inflammation and OM." (PMID 32117459, 2020). "A clinical association between polymorphisms in TLRs, the TLR4 coreceptor CD14, and tumor necrosis factor α (TNFα) has been described in children with recurrent otitis media." (PMID 25922834, 2015). "This indicated that the TNF-α, IL-1β, IL-6, IL-8 and IL-10 involved into inflammatory response in otitis media." (PMID 22173336, 2011). "It is well established that inhibiting TNF-alpha decreases middle ear inflammation in OM." (PMID 32117459, 2020). "Due to the important role of inflammatory molecules, such as TNF-α, that are highly expressed in cholesteatoma and closely related to the progression of adultacquired cholesteatoma, it can be assumed that immunoproteasomes’ activity also plays a role in otitis media." (PMID 37762439, 2023). "A histopathological analysis confirmed that treatment with the nanocarriers reduced the levels of pro-inflammatory cytokines (IL-1β, TNF-α, TLR4, IL-6) and raised the levels of antioxidant markers (Nrf-2, SOD) in an in vivo rat model of otitis media." (PMID 40143156, 2025). "However, Leffers, in his article on the immunomodulatory response of epithelial cells in otitis media, evaluated the immunohistochemical changes that occur in the epithelium after inoculation with Haemophilus influenzae, finding an increase in IL-1β, IL-6, IL-8, and TNFα." (PMID 40559231, 2025). "Expression of TNF-α and TLR2, which correlates with inflammation in otitis media, was up-regulated in the ears of mutant mice when examined by immunohistochemistry and semi-quantitative RT-PCR." (PMID 21818352, 2011). "Kadilya established a rat model of otitis media and reported that kukoamine A could alleviate inflammation in rats by reducing the levels of inflammation-related cytokines, such as interleukin-4 (IL-4), interferon-gamma (IFN-γ), and tumor necrosis factor-α (TNF-α), in a dose-dependent manner." (PMID 39473702, 2024).
overnutrition (19 papers, 2014 to 2025). An imbalanced nutritional status resulting from excessive intake of nutrients. "Multivariate regression models showed that the presence and loads of S. pneumoniae and M. catarrhalis were associated with higher concentrations of IL-6 in plasma and TNF-α in mucosal samples in children with overnutrition." (PMID 35886632, 2022). "Specifically, detection and loads of M. catarrhalis were associated with higher concentrations of IL-6 in plasma and TNF-α in nasopharyngeal samples only in children with overnutrition." (PMID 35886632, 2022). "Inflammaging refers to low-grade pro-inflammatory state in which cytokines such as TNF-α and IL-6 increase during the aging process, while metaflammation refers to metabolic inflammation due to metabolic diseases caused by overnutrition." (PMID 32961822, 2020). "In the myocardium, early overnutrition was associated with a significant increase in the gene expression of the proinflammatory markers IL-1β (p < 0.05), IL-6 (p < 0.01), TNF- α (p < 0.05), and LO (p < 0.05), and the pro-oxidant enzymes NOX-1 (p < 0.05) and NOX-4 (p < 0.01)." (PMID 32093229, 2020). "Genetic modification and overnutrition have proven the role of TNF-α in fatty liver disorders in both humans and animals." (PMID 38535313, 2024). "Overnutrition increases the levels of inflammatory molecules, such as TNF, IL-6, CCL2 and CCL3, in adipocytes, which activate resident macrophages, leading to the recruitment of more immune cells." (PMID 35112705, 2022). "Macrophages recruited with chronic overnutrition are pro-inflammatory (M1; CD11b+) and secrete tumor necrosis factor alpha (TNFα) that has been shown to contribute to IR in adipose, SkM, and liver." (PMID 29043068, 2017). "In contrast, at PND150, TNFα mRNA levels were significantly elevated in the perigonadal adipose of males that had been exposed to neonatal overnutrition." (PMID 27195103, 2016). "Overnutrition also leads to chronic inflammation, characterized by elevated interleukin (IL) 6, IL1β, and tumor-necrosis factor-α (TNFα)." (PMID 25541737, 2014). "Studies have shown that overnutrition can induce the nuclear transcription factor NF-κB to promote the expression of a variety of immune-inflammatory factors, such as TNF-α and IL-6, and trigger the tissue to enter a state of high immune-inflammatory activation." (PMID 35399795, 2022). "The intestinal proinflammatory cytokines IL-6 and TNF-α pathway may be a novel target for reversing offspring glucose abnormalities affected by in utero overnutrition." (PMID 33240638, 2020). "Overnutrition during pregnancy and lactation in mothers did not alter the levels of TNF-α in the hypothalamus in the offspring." (PMID 38201896, 2023).
scrub typhus (19 papers, 2012 to 2025). Scrub typhus is a rare dust mite-borne infectious disease caused by the Orientia tsutsugamushi bacterium and characterized clinically by an eruptive fever which is potentially serious. "Studies have shown elevated levels of TNF-α in patients with scrub typhus, correlating with disease severity and mortality risk." (PMID 40226813, 2025). "Particularly, high levels of TNF-α, IL-8, and IL-10 are positively associated with severe scrub typhus in humans." (PMID 37146079, 2023). "In summary, the present study demonstrates that circulating MAIT cells are activated, numerically deficient, and functionally impaired in TNF-α production in patients with scrub typhus." (PMID 27463223, 2016). "This study shows that circulating MAIT cells are activated, numerically deficient, and functionally impaired in TNF-α production in patients with scrub typhus." (PMID 27463223, 2016). "Finally, our study showed that the impaired production of TNF-α by MAIT cells was associated with elevated CD69 expression in scrub typhus patients." (PMID 27463223, 2016). "In scrub typhus patients, dominant Th1 immune responses have been observed, as evidenced by highly increased IFN-γ, TNF-α and CXCL10, while levels of Th2-associated chemokines were undetectable or marginally induced." (PMID 37426673, 2023). "Of note, even unstimulated CD4+ and CD8+ T cells showed increased expression of single effector cytokines (IFN-γ and TNF) reflecting the presence of activated effector T cells in peripheral blood of acute scrub typhus patients." (PMID 36961865, 2023). "Using murine models of scrub typhus, we demonstrated in this study the requirement of TNF-TNFR signaling in protective immunity against this infection." (PMID 35479068, 2022). "TNF levels have been reported as disease severity predictor in scrub typhus patients with very high serum levels during the acute phase of infection." (PMID 35925895, 2022). "To investigate the role of TNF-α signals in scrub typhus pathogenesis, we infected WT and TNFR1/2-/- mice and monitored disease progression." (PMID 35479068, 2022). "The serum TNF-α level in scrub typhus patients is considered a predictor of severe disease or death." (PMID 35479068, 2022). "In the present study, the production of IFN-α and TNF-α by pDCs upon CpG stimulation was found to be diminished in scrub typhus patients." (PMID 34276693, 2021). "The present study examined laboratory findings and tumor necrosis factor-alpha (TNF-α) levels of scrub typhus patients to identify the prognostic predictors of disease severity." (PMID 30909868, 2019). "Serum TNF-α levels were reportedly higher in patients with scrub typhus compared those in a normal control group, while another study showed a strong correlation between serum TNF-α level and disease severity in the acute phase of scrub typhus." (PMID 30909868, 2019). "That is, elevated serum TNF-α, CRP level, and modified APACHE II score were associated with poor prognosis in patients with scrub typhus." (PMID 30909868, 2019). "Next, we measured plasma levels of IFN-γ, IL-17, and IFN-γ-inducing cytokines, such as IL-12, IL-18 and TNF-α, in 25 patients with scrub typhus and 15 age- and sex-matched HCs using Luminex assay and ELISA." (PMID 28750012, 2017). "Percentages of TNF-α+ MAIT cells were found to be significantly lower in scrub typhus patients than in HCs (median 15.6% versus 45.0% [p < 0.05])." (PMID 27463223, 2016). "Based on our observation that circulating MAIT cell levels and TNF-α production are reduced in scrub typhus patients, we investigated the changes in circulating MAIT cell levels and functions in relation to disease activity." (PMID 27463223, 2016). "Proinflammatory cytokines, such as TNF-α, IL-1β and interleukin-6 (IL-6), increase markedly in patients with scrub typhus, and attribute to the high fever occurring in most scrub typhus patients." (PMID 22723924, 2012).
scrub typhus (continued). "As O. tsutsugamushi sensitizes cells to necroptosis, the increased TNF levels in symptomatic scrub typhus may induce necroptosis of infected cells, which could promote bacterial spread." (PMID 40430799, 2025). "But, serum TNF-α levels in scrub typhus patients were positively correlated with disease severity." (PMID 35479068, 2022). "High levels of several cytokines, including IL-6, IL-8, IL-10, monocyte chemoattractant protein-1 (MCP-1), macrophage inflammatory protein-1 beta (MIP-1β), IFN-γ and TNF were reported during the acute phase of scrub typhus patients, and correlated with disease severity." (PMID 35925895, 2022). "In addition, the percentages of IL-12+ and TNF-α+ cDCs were found to be significantly lower in scrub typhus patients compared to HCs (for IL-12+ cells, median 9.3% versus 28.8%, P = 0.003; for TNF-α+ cells, median 24.7% versus 49.0%, P = 0.019)." (PMID 34276693, 2021). "In addition, the production of IFN-α and TNF-α by circulating pDCs, and IL-12 and TNF-α by circulating cDCs was reduced in scrub typhus patients." (PMID 34276693, 2021). "In addition, following IFN-γ/LPS stimulation, cDCs exhibited the reduced production of IL-12 and TNF-α in scrub typhus patients." (PMID 34276693, 2021). "In conclusion, this study showed that an elevated serum TNF-α level can predict severe scrub typhus or death due to the disease, confirming that it may be useful for the prediction of the prognosis of scrub typhus patients." (PMID 30909868, 2019). "An elevated serum TNF-α level in patients with scrub typhus could predict a severe condition or death and may be useful in predicting patient prognosis." (PMID 30909868, 2019). "Therefore, the present study investigated the significance of serum TNF-α level as a predictor of disease severity in patients with scrub typhus, including deceased patients, and identified other predictors of disease severity." (PMID 30909868, 2019). "Moreover, data on the significance of TNF-α level as a prognostic predictor of the severity of scrub typhus is insufficient." (PMID 30909868, 2019). "A previous study reported that patients with scrub typhus had higher serum TNF-α concentrations compared to those of a normal control group; similarly, another study observed a strong correlation between serum TNF-α level and disease severity in the acute phase of scrub typhus." (PMID 30909868, 2019). "Moreover, the plasma levels of IFN-γ, IL-12, IL-18 and TNF-α were significantly higher in scrub typhus patients than in HCs." (PMID 28750012, 2017). "Previous studies have shown increased plasma or serum levels of various cytokines in scrub typhus patients such as TNFα, IFNγ, IL-6 and IL-10, but these studies included a rather low number of patients (n = 9–55) and relatively few inflammatory mediators were examined." (PMID 24516677, 2014). "Therefore, the present study investigated whether the laboratory findings and TNF-α level in patients with scrub typhus have significance as prognostic predictors of disease severity." (PMID 30909868, 2019). "Several inflammatory cytokines such as TNFα are potent inducers of IL-10, and whether high IL-10 levels in scrub typhus patients reflects the degree of inflammatory stimuli as a counteracting mechanism or whether high IL-10 could attenuate microbe killing is at present unclear." (PMID 24516677, 2014). "In scrub typhus patients, proinflammatory cytokine and chemokine responses are characterized by upregulation of IFN-γ, TNF-α, IL-6, IL-8, IL-12p40, CXCL10, MCP-1, and MIP-1β, but downregulation of Th2-associated cytokines and chemokines." (PMID 37146079, 2023). "By applying the optimised WBA protocol to a clinical study of scrub typhus we demonstrate that the main source of IFN-γ and TNF upon HI-WCA-OT stimulation of WB are CD4+ T cells." (PMID 36961865, 2023).